EZH2 (enhancer of zeste 2 polycomb repressive complex 2 subunit)
Diseases named in the same sentence as EZH2 in open-access papers (continued):
Sharing a sentence is not in itself a finding about the gene and the disease.
prostate carcinoma (continued). "One of the most prevalent genetic alterations in prostate cancer is the TMPRESS2-ERG fusion, caused by chromosomal translocation on chromosome 21, which has been shown to activate EZH2 expression 56-57." (PMID 40959108, 2025). "Beyond its anti-proliferative activity, EZH2 inhibition has been shown to suppress migration and invasion of prostate cancer cells." (PMID 40959108, 2025). "Otherwise, EZH2 suppression leads to increased activated CD8+ T cells, increased M1 tumor-associated macrophages and enhanced response to PD-1 therapy in prostate cancer." (PMID 40959108, 2025). "EZH2 is highly overexpressed in prostate cancer, colorectal cancer, and several other cancers and promotes carcinogenesis by repressing tumor suppressor genes, such as p21 and p16." (PMID 39934895, 2025). "EZH2 regulates numerous genes that contribute to prostate cancer development by transcriptionally inhibiting tumor metastasis." (PMID 40959108, 2025). "Restoration of miR-26a-5p by EZH2 silencing can block the IL-6/STAT3 axis to inhibit prostate cancer growth." (PMID 40652273, 2025). "Research has demonstrated that TPL hinders the growth of prostate cancer (PCa) cells and reduces the expression of EZH2." (PMID 38678240, 2024). "Enhancer of zeste homolog 2 (EZH2) is a histone methyltransferase and emerging therapeutic target that is overexpressed in most castration-resistant prostate cancers and implicated as a driver of disease progression and resistance to hormonal therapies." (PMID 38405800, 2024). "EZH2 phosphorylation, occurring on T350 residue, which is catalyzed by CDK1 or CDK2, is required for EZH2-mediated H3K27me3 modifications in prostate cancer cells." (PMID 39769907, 2024). "For instance, in advanced prostate cancer, EZH2 participates in gene repression in an enzyme-activity-dependent manner, but also acts as a transcriptional activator to occupy promoters of androgen receptor genes." (PMID 39072246, 2024). "The upregulation of EZH2 by HIF-1α is also observed in prostate cancer (PCa) cells while exposed to hypoxia." (PMID 38911968, 2024). "In prostate cancer, EZH2 is known to collaborate with AR in promoting the progression of AR-positive CRPCs through both H3K27me3-dependent and -independent mechanisms." (PMID 38777812, 2024). "In this study, we sought to define the mechanism of action of EZH2 in both PRAD and NEPC to determine how the underlying lineage state can impact EZH2 function and response to EZH2 inhibition in prostate cancer." (PMID 38405800, 2024). "Taken together, EZH2 plays a critical role in lineage plasticity both in prostate cancer and SCLC–NEtD." (PMID 39372390, 2024). "Clinically, EZH2 firstly discovered involving in prostate cancer and is a major transcriptional target of the E2F-PRB tumor-suppressor pathway." (PMID 38629070, 2024). "A number of EZH2 inhibitors are being evaluated in clinical trials for castration-resistant prostate cancer, and all of these trials are biomarker-unselected (NCT04846478, NCT04179864, NCT03460977)." (PMID 38405800, 2024). "Dysregulation of the EZH2 gene has been observed in various cancer types, including lymphoma, breast, and prostate cancer, which implies that EZH2 is a promising anticancer target." (PMID 39518098, 2024). "EZH2 is overexpressed in most castration-resistant prostate cancers including in NEPC and has emerged as a therapeutic target." (PMID 38405800, 2024). "Several factors promoting EZH2 activation in prostate cancer have been reported, including the upregulation of N-Myc, ASCL1 and SOX216,20,21." (PMID 38238517, 2024). "EZH2 expression has also been correlated with the aggressiveness and metastasis capacity of breast and prostate cancers." (PMID 39769907, 2024). "Particularly, TRAF6, initially recognized as a cytoplasmic adapter protein, has recently been established as a key regulator of EZH2 stability in breast and prostate cancers." (PMID 39043634, 2024).
prostate carcinoma (continued). "EZH2 overexpression was demonstrated for the first time in the context of prostate cancer and later on observed in many other solid tumors such as breast, lung, hepatocellular, colorectal, and pancreatic cancers, as well as hematological cancers." (PMID 39769907, 2024). "The results demonstrated that NCAPD3 promoted tumor growth in prostate cancer through down-regulating miR-30a-5p, which was associated with the regulation of STAT3, MYC, and EZH2." (PMID 38561330, 2024). "For instance, EZH2 has been observed to positively regulate androgen receptor gene expression in castration-resistant prostate cancer." (PMID 39120328, 2024). "Metformin hinders metastasis of prostate cancer cells by stimulating the expression of histone methyltransferase SETD2 (SET Domain Containing 2) while decreasing EZH2 (Enhancer of Zeste Homolog 2) and H3K27me3 levels." (PMID 36959680, 2023). "Overexpression of EZH2 in prostate cancer promotes its progression whereas downregulation of EZH2 inhibits cell proliferation, cell cycle, and invasion in vitro, and tumor reduction in vivo." (PMID 36672280, 2023). "Currently, several EZH2 inhibitors have been developed for the treatment of hematological malignancies, prostate cancer, sarcoma, and other advanced solid tumors." (PMID 37210576, 2023). "Analysis of transcriptional profiles from a panel of prostate cancers and normal prostate tissue confirms this pattern of expression and reveals that 92% of metastatic samples express EZH2 at levels ≥3 SD higher than those observed in normal prostate tissue." (PMID 37104245, 2023). "EZH2 is a protein, which has functional activity important to both neurogenesis and aggressive prostate cancer." (PMID 37484909, 2023). "EZH2 is overexpressed in prostate cancer and protein levels appear to progressively increase in advanced tumors." (PMID 37104245, 2023). "Some studies have shown that DZNep exhibits good anti-tumor properties by inhibiting EZH2 in breast cancer, lung cancer, prostate cancer, colon cancer, and other cancer cells." (PMID 36672374, 2023). "EZH2 targets the metastasis suppressor RKIP promoter in prostate cancer and negatively regulates RKIP transcription by inhibiting histone modifications." (PMID 37190171, 2023). "Since EZH2 acts as an oncogene in prostate cancer, we correlated INPP4B and EZH2 expression in indolent and aggressive human prostate cancers." (PMID 38001678, 2023). "initially found that EZH2 expression was highly correlative with progression of castration-resistant prostate cancer." (PMID 37664059, 2023). "For instance, KDM8 / JMJD5, a histone lysine demethylase/dioxygenase, directly targets ATAD2 to maintain cell survival via AR activation of EZH2 in prostate cancer." (PMID 36632213, 2023). "EZH2 overexpression promotes castration resistance in prostate cancers via various mechanisms, including inducing epithelial-to-mesenchymal transition (EMT), increased stem cell potential, and androgen receptor pathway activation." (PMID 37104249, 2023). "RACGAP1 promoted neuroendocrine transdifferentiation of prostate cancer by stabilizing EZH2 expression in the ubiquitin-proteasome pathway." (PMID 37196108, 2023). "In men, there is a positive correlation between the expression of INPP4B and EZH2 in primary prostate cancers." (PMID 38001678, 2023). "EZH2 is an oncogene in prostate cancer, and its expression increases with the progression to metastatic disease." (PMID 38001678, 2023). "This study showed that Tyr641 mutations were linked to a significant decrease in EZH2 enzymatic activity in vitro, in apparent contradiction to the elevated EZH2 mRNA levels seen in breast and prostate cancer." (PMID 37830606, 2023).
prostate carcinoma (continued). "Other studies highlighted the oncogenic function of the methyltransferase EZH2 in castration-resistant prostate cancer cells, where EZH2 acts as a coactivator for critical transcription factors, including the androgen receptor." (PMID 37894361, 2023). "In prostate cancer, EZH2 promotes progression via its dual roles: its canonical role in epigenetic silencing of tumor suppressor genes as well as its noncanonical role as a transcription factor in activating AR transcription." (PMID 37210576, 2023). "Androgen deprivation also reduced EZH2 protein and mRNA levels in two independently derived androgen-dependent prostate cancer cell lines: LNCaP and VCaP." (PMID 38001678, 2023). "Knockdown of INPP4B reduces the EZH2 in prostate cancer cell lines on both the RNA and protein levels." (PMID 38001678, 2023). "In prostate cancers, EZH2 has dual functions in that it acts as a transcriptional activator mediated by the induction of AR-regulated genes and as a gene silencer mediated by the epigenetic modification suppression of AR-regulated genes." (PMID 36678591, 2023). "The results suggested that high expression of SNHG4 was correlated with RRM2/EZH2/AURKA/TK1 overexpression in prostate cancer tissue specimens." (PMID 37596700, 2023). "The roles of EZH2 in prostate cancer with neuroendocrine features were investigated in several studies." (PMID 37240468, 2023). "The interaction between BLM and EZH2 reportedly affects the occurrence and development of prostate cancer." (PMID 36750200, 2023). "Although the mechanism is different, the activation of STING upon treatment with EZH2 inhibitors has been also reported in prostate cancer." (PMID 36900330, 2023). "Prostate cancer is a common tumor among men and EZH2 has been shown to play a role in its malignancy affecting growth and senescence." (PMID 35236381, 2022). "Recently, it was reported that SETD2 regulates the deposition of H3K36me3 by interacting with hnRNPL, and that SETD2 suppresses metastatic progression of prostate cancer by methylating EZH2 to lead its degradation." (PMID 35216000, 2022). "EZH2 upregulation in prostate cancer cells results in the induction of hexokinase-2 (HK2) to increase glycolysis." (PMID 35236381, 2022). "The therapeutic targeting of miRNA/EZH2 axis has been shown to suppress prostate cancer progression." (PMID 35236381, 2022). "The expression of miRNA-605-3p as a tumor-suppressor factor is down-regulated in prostate cancer cells, which increases the expression of EZH2 to disrupt prostate cancer growth and metastasis." (PMID 35236381, 2022). "miR-26a as an apoptosis inducer is another regulator of EZH2, and its diminished levels of this miRNA have been found in lung cancer, rhabdomyosarcoma, and prostate cancer." (PMID 35087589, 2022). "We have previously shown that the tissue gene expression levels of the genes TOP2A and EZH2 can identify an aggressive subgroup of prostate cancer." (PMID 36251389, 2022). "In recent years, a number of clinical studies have focused on targeting epigenetic factors in prostate cancer, including EZH2, in combination with hormone therapy." (PMID 35477723, 2022). "To further investigate the relationship between EZH2 and PCa, we classified the prostate cancer patients into high-expression and low-expression groups based on the median EZH2 expression levels of all patients." (PMID 36358967, 2022). "Overexpression of EZH2 has been identified in various cancers, including gastric cancer, thyroid carcinoma, prostate cancer, and HCC." (PMID 35656182, 2022). "Whilst EZH2 represents a major target for prostate cancer, alternative targets include histone acetyl transferase E1A binding protein (p300) and CREB binding protein (CBP)." (PMID 35547880, 2022). "In a recent study by Morel and colleagues, inhibition of EZH2 restored the expression of ISGs and reversed the resistance to ICB treatments, highlighting the therapeutic potential of EZH2 inhibitors in prostate cancer." (PMID 35547880, 2022).
prostate carcinoma (continued). "LncRNA Small Nucleolar RNA Host Gene 1 (SNHG1) activates Wnt/β-catenin and PI3K/Akt/mTOR signaling pathways by targeting EZH2 (Enhancer of zeste homolog 2), and promoting proliferation, apoptosis and autophagy of prostate cancer (PCa) cells." (PMID 35309939, 2022). "More specifically, in prostate cancer, the polycomb repressive complex subunit Enhancer of Zeste homolog 2 (EZH2) is bound to the miR-708 promoter* and represses its expression." (PMID 36553642, 2022). "Similar repression of TIMPs via EZH2 overexpression has been observed in ovarian and prostate cancers." (PMID 36066973, 2022). "The first clinically relevant finding in the PcG protein field was that EZH2 promoted prostate cancer progression and poor prognosis." (PMID 36076977, 2022). "These two phosphorylation events are activated in prostate cancer and natural killer/T-cell lymphoma cells, respectively, converting EZH2 from a gene repressor to a gene activator." (PMID 35800061, 2022). "In prostate cancer, the EZH2 inhibitors combined with PD-1 immunotherapy further improved patient prognosis." (PMID 36532284, 2022). "MiRNA-137-3p down-regulates EZH2 expression via c-Jun N-terminal kinase 3 (JNK3) inhibition which significantly suppresses prostate cancer proliferation and metastasis, while stimulating apoptosis." (PMID 35236381, 2022). "Studies have shown that increased EZH2 expression and activity are key events in prostate cancer initiation and progression." (PMID 35892678, 2022). "Our latest study also identified the interaction between NCAPD3 and E2F1 in prostate cancer which increased the binding of E2F1 to the promoter of EZH2." (PMID 35689245, 2022). "Using univariate and multivariate Cox regression analysis, we determined that EZH2 can be an independent prognostic factor for prostate cancer." (PMID 36358967, 2022). "MiR-200c was regulated by EZH2 through epigenetic repression in prostate cancer, and miR-200c directly controlled the expression of E2F3 by targeting 3′UTR." (PMID 36316365, 2022). "The inhibition of EZH2 upregulates the induction of IFN-stimulated genes in prostate cancer and promotes a marked increase in CD4+ and CD8+ T cells in the TME, reversing the anti-PD-1 therapy resistance of B6-HiMYC PCa transgenic tissue transplant model." (PMID 35892678, 2022). "The epigenetic and chromatin regulators CHD1, SWI/SNF, and EZH2 likewise play important roles in the evolution of the AR cistrome and prostate cancer biology." (PMID 36212399, 2022). "Increasing evidence supports a close relevance between EZH2 expression and human malignancies, for instance that of EZH2 was highly expressed in bladder, breast, endometrial, and prostate cancer correlating with tumor progression." (PMID 35449124, 2022). "First, we analyzed the expression of G9a and EZH2 in breast, colon, and prostate cancers, according to The Cancer Genome Atlas (TCGA) database." (PMID 35409271, 2022). "In breast and prostate cancer, EZH2 drives transcriptional activation by interacting with NF-κB and the androgen receptor, respectively, and recent findings suggest that EZH2-cMYC complexes co-activate joint gene signatures, thus promoting acute leukemia." (PMID 35884510, 2022). "For example, Burkhart and colleagues demonstrated increased EZH2 expression and H3K27me3 levels in genetically engineered mouse models of prostate cancer relative to age-matched wild-type mice." (PMID 36212399, 2022). "Luteolin has depicted increased expression of MiR-26a, which is a regulator of EZH2, and at the same time, it has inhibited EZH2 and H3K27me3, leading to self-programmed death and cycle arrest and apoptosis in prostate cancer cells." (PMID 35409426, 2022). "Recent researches have found that the expression of EZH2 is significantly upregulated in advanced prostate cancer with distant metastases, supporting the clinical relevance of poor diagnosis the emergence of NEPC in enzalutamide-induced models." (PMID 35633416, 2022).
prostate carcinoma (continued). "In turn, miRNA-26a binds to 3′-UTR of EZH2 to reduce its expression and impair prostate cancer proliferation." (PMID 35236381, 2022). "For instance, as a tumor-suppressor, lncRNA MEG3 binds to EZH2 resulting in H3K27-mediated trimethylation of Engrailed-2 (EN-2) to suppress prostate cancer progression." (PMID 35236381, 2022). "HOTAIR contributes to Polyphyllin I-inhibited growth of castration-resistant prostate cancer cells by regulating DNMT1 and EZH2 in prostate cancer." (PMID 34405017, 2021). "In pre-clinical studies, EZH2 is found to be overexpressed in docetaxel-resistant prostate cancers cells, cisplatin-resistant breast cancer cells and 5-FU resistant gastric cancer cells." (PMID 34439236, 2021). "EZH2 inhibition across a variety of therapy-resistant prostate cancers shows promising results, particularly to reverse chemotherapy and radiotherapy resistance." (PMID 34617019, 2021). "Other studies have addressed that the positive correlations between EZH2 and miRNAs, for example miR-181b in prostate cancer and miR-101-3p in GC, have been indicated to have tumor suppressive properties at molecular levels." (PMID 33882457, 2021). "An important example of miRNA epigenetic regulation in prostate cancer is miR-101 regulation of enhancer of zeste homolog 2 (EZH2)." (PMID 33672595, 2021). "EZH2 interacts and cooperates with N-Myc to reduce the expression of N-Myc target genes and drives neuroendocrine plasticity in prostate cancer." (PMID 34298815, 2021). "Overexpression of miR-137-3p inhibits the tumor growth of prostate cancer by regulating the JNK3/EZH2 signal pathway." (PMID 33968763, 2021). "Subsequent studies of prostate cancer demonstrated that high EZH2 and SUZ12 expression correlate with metastasis progression, and for EZH2high, with poor survival prognosis." (PMID 34202528, 2021). "The significance of non-canonical activities of EZH2 is further demonstrated for castration-resistant prostate cancer cells in which the oncogenicity of EZH2 is related to its role as transcription factor." (PMID 35008205, 2021). "To further understand the relevance of these findings in human tumors, we examined the expression of the ERG/EZH2 target genes in transcriptomic data from prostate cancer patients." (PMID 34230470, 2021). "In prostate cancer, EZH2 inhibition together with PD-1 inhibition significantly enhanced the anti-tumour response with observed intratumoral trafficking of activated CD8+ T-cells and TAMs." (PMID 34439236, 2021). "Ultimately, knockdown experiments demonstrated that EZH2-MALAT1 association played a significant role in cancer progression, thus representing a new alternative target for treating prostate cancer." (PMID 33803328, 2021). "Chromatin immune-precipitation and parallel sequencing showed that TMPRSS2–ERG was involved in the development of prostate cancer through disruption of lineage-specific differentiation and potentiation of the EZH2-mediated de-differentiation program." (PMID 34399734, 2021). "Consistently, ERG/EZH2 co-regulated target genes are deregulated preferentially in tumors with concomitant ERG gain and PTEN loss and in castration-resistant prostate cancers." (PMID 34230470, 2021). "PRC2-independent functions for EZH2 have also been identified in prostate cancer, where EZH2 acts as co-activator of the androgen receptor." (PMID 33614973, 2021). "Enhancer of Zeste Homolog 2 (EZH2) is a critical player in the early steps of neuroendocrine differentiation in prostate cancer." (PMID 33572108, 2021).